IL6 (interleukin 6)
Diseases named in the same sentence as IL6 in open-access papers (continued):
Sharing a sentence is not in itself a finding about the gene and the disease.
gastric cancer (continued). "Meanwhile, another study showed that the increased expression of IL-6 in trastuzumab-resistant human gastric cancer (NCI-N87-R) cell line induced the expression of JAGGED 1, which then in turn further promoted the expression of IL-6." (PMID 32855763, 2020). "In gastric cancer, CAFs also influence carcinogenesis through IL-6 induction in metastasis and invasion through factor overexpression increasing the epithelial-mesenchymal transition (EMT), finally activating the JAK2/STAT3 pathway." (PMID 32499779, 2020). "Trastuzumab treatment rendered resistance to itself, facilitated epithelial-to-mesenchymal transition and enhanced metastatic potential in gastric cancer cells through an IL6/STAT3/Jagged-1/Notch positive feedback loop." (PMID 32872659, 2020). "High IL6/IL10 ratio in H. pylori-infected patients indicated that pro-inflammatory cytokines play a fundamental role in gastric cancer development." (PMID 33569347, 2020). "Our results demonstrate that acupuncture and moxibustion contributes to inhibiting progression and improving prognosis of advanced gastric cancer by reversing Th1/Th2 shift and downregulating IL-6, CRP, and Ca199." (PMID 33144870, 2020). "Lastly, in gastric cancer, CAFs secrete IL-6 inducing resistance to 5-fluorouracil or cisplatin, with inhibition of its receptor (IL-6R), suppressing drug resistance." (PMID 32499779, 2020). "In this study including 140 patients with gastric cancer receiving EN and probiotics for 8 days, the decrease in the incidence of diarrhoea and reduction of the pro-inflammatory cytokines level (IL-6, IL-8, and TNF-α) in the postoperative period were reported." (PMID 32917221, 2020). "Our data are also in line with a recent study showing that IL-6 produced by CAFs can enhance the chemoresistance of gastric cancer cells by activation of STAT352." (PMID 32528731, 2020). "As an inflammation hallmark and direct target of IL-6 signaling, CRP is closely related to progression in a wide variety of cancers including gastric cancer." (PMID 33144870, 2020). "High IL-6 expression in resected gastric cancer tissue is correlated with poor chemotherapy response in patients." (PMID 32528731, 2020). "The anti-inflammatory role of DFMO highlights the injurious effect of inflammation in gastric cancer development and the need to reduce gastric inflammation for cancer prevention by inhibiting IL-6." (PMID 32231118, 2020). "As a result, IL-6 inhibitors can serve as a therapy against gastric cancer, in addition to lowered capsaicin intake and pathogen clearance." (PMID 32231118, 2020). "Recent studies have demonstrated that the proinflammatory cytokine interleukin (IL)-6 plays an important role in the tumour progression and metastasis of multiple cancers, including gastric cancer." (PMID 32636937, 2020). "In patients with gastric cancer (GC), IL-6 and IL-8 activate CD45+CD33lowCD11bdim MDSCs, thereby inducing Arg1 release accompanied by activation of the PI3K-AKT signaling pathway." (PMID 32488850, 2020). "IL-6 expression is markedly associated with STAT3 and enhances the invasion of gastric cancer cells 48,49." (PMID 31892988, 2020). "The anti-inflammatory potential of DFMO against gastritis and, therefore, against gastric cancer was evaluated by analyzing IL-6 and IFN-γ status." (PMID 32231118, 2020). "MDSCs suppresses cytolytic T lymphocytes (CTL) activity via interleukin 6 (IL6)/IL8-arginase (Arg) axis to promote gastric cancer cell progression." (PMID 32595638, 2020). "Accordingly, in MNU-induced mice gastric tumors and human clinical gastric cancer tissues, we observed increased expression of NFATc2 and IL-6 in tumor cells, indicating an autocrine pathway was activated in tumorigenesis." (PMID 32041943, 2020). "Similar observations were made in gastric cancer where CAF-secreted IL-6 induced EMT and metastasis through STAT-3 pathway activation." (PMID 33553157, 2020).
gastric cancer (continued). "DFMO appears to act as an anti-inflammatory agent to prevent capsaicin-associated gastric cancer development by targeting COX-1 and COX-2 and by regulating IL-6 and IFN-γ expression." (PMID 32231118, 2020). "In gastric cancer, estrogens stimulate CAFs secretion of IL-6, thereby promoting signal transducer and activator of transcription (STAT)-3 pathway-dependent cancer cells proliferation and invasion." (PMID 33553157, 2020). "Altogether, our results showed that acupuncture and moxibustion can inhibit gastric cancer development by promoting Th1 dominance and decreasing tumor marker Ca199 and proinflammatory factors IL-6 and CRP." (PMID 33144870, 2020). "To characterize the content of these exosomes we performed a cytokine array which identified a number of candidate proteins plausibly related to omental- induced gastric cancer metastasis; of them, IL-6 and IL-8 were the most abundant." (PMID 31803630, 2019). "Amongst these cytokines, IL-1β induced VEGF production in gastric cancer cells through Erk- and p38-dependent pathways, and IL-6 dose-dependently induced VEGF release from platelets, further linking the processes of inflammation with angiogenesis." (PMID 31757048, 2019). "Gastric cancer-derived exosomes induced NF-kB activation in macrophages, leading to an increase in the expression of pro-inflammatory factors such as IL-6 and TNF-a, in turn promoting the proliferation of gastric cancer cells." (PMID 30987213, 2019). "Together, these results indicate that knockdown of DYNC1I1 suppressed cell growth and migration of gastric cancer cells by regulating the secretion of IL-6." (PMID 31249807, 2019). "In this study, we reported for the first time that the polarization and generation of pro-tumor M2-like macrophages was strikingly triggered by GC-MSCs in gastric cancer through activation of the JAK2/STAT3 signaling pathway via high secretion of IL-6/IL-8." (PMID 31801938, 2019). "In this study, we analyze the anti-cancer properties of LPE on migration and invasiveness in MKN-28 and AGS human gastric cancer cell lines either in the absence or presence of the pro-inflammatory cytokine IL-6." (PMID 31817563, 2019). "The authors suggest that the increased MPV in gastric cancer patients can be a sequel of inflammatory condition and the accompanying elevated level of IL-6." (PMID 31148950, 2019). "On the other hand, it has been also reported that gastric cancer-derived exosomes activate the NF-kB pathway in recipient macrophages, leading to up-regulation of pro-inflammatory factors such as IL-6 and TNF-α which promote gastric cancer progression." (PMID 31686989, 2019). "Our study showed that tumor-promoting GC-MSCs contribute to M2 macrophage polarization within the gastric cancer niche through considerable secretion of IL-6 and IL-8." (PMID 31801938, 2019). "In the present study, we highlight the unique ability of stromal GC-MSCs to induce the polarization of macrophages into a pro-tumor M2 subtype within the gastric cancer niche through the secretion of IL-6 and IL-8 via the JAK2/STAT3 signaling pathway." (PMID 31801938, 2019). "As the inflammatory cytokine IL-6 also promotes migration and invasiveness of gastric cancer cells, we analyzed the effect of LPE in the IL-6 stimulated human gastric AGS and MKN-28 cell lines." (PMID 31817563, 2019). "Taken together, these results showed that DYNC1I1 controls IL-6 expression levels by regulating NF-κB/p65 nuclear translocation in gastric cancer cells." (PMID 31249807, 2019). "IL-6 promotes e-cadherin repression and treating human gastric carcinoma cells with exogenous IL-8 decreased expression of E-cadherin mRNA." (PMID 31261642, 2019). "After 1 year, 69% of the gastric cancer patients with high IL-6 levels were alive compared to 94% of the gastric cancer patients with low serum IL-6, and after 3 years, the survival rates were 43% and 87%, respectively." (PMID 30038723, 2018).
gastric cancer (continued). "For instance, gastric cancer-derived exosomes were shown to induce NF-κB activation in macrophages, leading to an increase in the expression of pro-inflammatory factors such as IL-6 and TNF-α, in turn promoting the proliferation of gastric cancer cells." (PMID 29515996, 2018). "Gastric cancer cells secrete IL-6, and an increase of IL-6 in serum and gastric cancer tissue appears to regulate tumor growth and development in an autocrine loop." (PMID 30038723, 2018). "Previous studies reported that NF-κB activation in macrophages increase the expression of cytokines such as TNF-α and IL-6, in turn promoting the proliferation of gastric cancer cells." (PMID 30266897, 2018). "Six out of the 10 studies investigating gastric cancer and IL-6, assessed the correlation between clinical characteristics in patients with gastric cancer and IL-6, all showing a significant correlation." (PMID 30038723, 2018). "Gastric cancer cells stimulated by IL-6 showed enhanced ability of migration compared with gastric cancer cells alone." (PMID 28186964, 2017). "We further quantified expression levels of IL-6 in CAFs, normal fibroblasts (NFs) and gastric cancer cells (SNU-1, MKN45, SGC7901 and MKN28) by ELISA." (PMID 28186964, 2017). "Here, we show that CAFs isolated from gastric cancer produce significant amounts of interleukin-6 (IL-6)." (PMID 28186964, 2017). "In gastric cancer, the stromal fibroblasts can give rise to IL6 expression by epigenetic silencing of miR-149." (PMID 28333977, 2017). "To further illustrate which cell component(s) in gastric cancer tissues is (are) responsible for the high expression of IL-6, we detected IL-6 expression in tissues by immunofluorescence staining." (PMID 28186964, 2017). "In the present study, we have shown that IL-6 secreted by CAFs induced EMT of gastric cancer cells, which is characterized by losing epithelial markers E-cadherin and acquiring of mesenchymal markers N-cadherin and ZEB2." (PMID 28186964, 2017). "Reduced STING expression rendered gastric cancer cells a defective function to produce type I interferon and other immune cytokines such as IL-6 after exposure to cytosolic DNA or its agonist cGAMP." (PMID 28176788, 2017). "MiR-149 is down-regulated in gastric cancer CAFs; it inhibits fibroblast activation by down-regulating IL-6." (PMID 28851377, 2017). "In this study, we reveal that IL-6 was overexpressed in both serum and cancer tissue of gastric cancer patients, and significantly higher expression was found in stromal fibroblasts." (PMID 28186964, 2017). "In this study, we demonstrate that IL-6 secreted by CAFs plays an important role in the progression of gastric cancer." (PMID 28186964, 2017). "Another study by Zhu and colleagues has demonstrated the interaction between gastric cancer-derived mesenchymal stem cells (GC-MSCs) and neutrophils via the IL6/STAT3 axis." (PMID 28687755, 2017). "To determine the expression level and cellular source of IL-6 in gastric cancer, we first detected IL-6 expression in both serum and cancer tissues in gastric cancer patient by ELISA." (PMID 28186964, 2017). "Researchers also showed that CAFs induced EMT in gastric cancer cells via secreting IL-6 that activated JAK2/STAT3 signaling pathway." (PMID 29383119, 2017). "A slightly higher serum cutoff of this cytokine was identified as having the potential to diagnose preoperative gastric cancer and to evaluate prognoses after surgical tumor removal: 6.77 pg/mL serum IL-6 (sensitivity 85.7%)." (PMID 28487810, 2017). "IL-6 levels in the serum of gastric cancer patients were significantly elevated in comparison with healthy volunteers." (PMID 28186964, 2017). "High serum concentrations of IL-6 have been described for several solid tumors such as lung, breast, pancreatic and gastric cancer." (PMID 28537901, 2017).
gastric cancer (continued). "Oestrogen has been shown to impair CCL5‐ and IL6‐induced gastric cancer cell motility 28, 29, and reduce gastric cancer progression through suppression of erbB‐2 oncogene activation." (PMID 26945908, 2016). "Differentiation of Th17 cells of IL‐6‐dependent manner was demonstrated in gastric myofibroblasts/fibroblasts isolated from infected gastric cancer mucosa." (PMID 26945693, 2016). "In gastric cancer, IL-6 released by CAFs is able to modify the phenotype of tumor cells using IL-6/JAK/STAT3 signaling." (PMID 27023622, 2016). "For the molecular mechanisms, CDDP alone increased the cancer stem cell (CSC)-like properties in gastric cancer cells via activating the interleukin-6 (IL-6)/IL-6 receptor (IL-6R)/signal transducer and activator of transcription 3 (STAT3) signaling." (PMID 27824145, 2016). "IL-6 plays a key role as prognostic factor even in gastric cancer invasion and metastasis and its elevated level in circulation predicts shorter survival." (PMID 27034885, 2016). "Pre-treatment with IL-6 stripped the hUC-MSCs of their growth-promoting effect on gastric cancer cells." (PMID 25483835, 2015). "In the present study, we focused on the phenotype and function of human umbilical cord-derived MSCs hUC-MSCs pre-treated with IL-6 in gastric cancer." (PMID 25483835, 2015). "To confirm the role of IL-6-hUC-MSCs in gastric cancer cells in vivo, we co-injected SGC-7901 gastric cancer cells with hUC-MSCs or IL-6-hUC-MSCs into BALB/c nude mice to establish a subcutaneous tumor xenograft model of gastric cancer." (PMID 25483835, 2015). "In the present study, we pre-treated hUC-MSCs with IL-6 and investigated the phenotype and function in gastric cancer development in vitro and in vivo." (PMID 25483835, 2015). "In a gastric cancer cell line, IL-6 inhibited apoptosis through inhibition of JNK signalling and subsequent cell death." (PMID 26382031, 2015). "The findings of this study provide new insight into the role of the inflammatory cytokine, IL-6, in the tumor-promoting effects of MSCs and its function in gastric cancer." (PMID 25483835, 2015). "In order to reveal the role of IL-6-pre-treated hUC-MSCs in gastric cancer, we co-cultured MNNG-transformed precancerous GES-1 cells or SGC-7901 gastric cancer cells with hUC-MSCs or IL-6-hUC-MSCs." (PMID 25483835, 2015). "Using a cell coculture system, a group of researchers have identified critical stromal factors that modulate cancer growth positively and negatively, showing that gastric stromal cells secreted IL-6 as a growth and survival factor for gastric cancer cells." (PMID 26347589, 2015). "While IL-6 stimulated the growth and survival of almost all gastric cancer cell lines used here, GAPDH suppressed the growth of MKN-7 and MKN-28 cells." (PMID 25785838, 2015). "In order to determine the effect of IL-6-hucMSC on gastric cancer cells, we co-cultured the SGC-7901 gastric cancer cells with hUC-MSCs or IL-6-hUC-MSCs in a Transwell plate for 48 h." (PMID 25483835, 2015). "Using a cell co-culture system, we found that gastric stromal cells secreted IL-6 as a growth and survival factor for gastric cancer cells." (PMID 25785838, 2015). "In this study, as the majority of bacterial pathogens mediate STAT3 activation via autocrine IL-6, it was found that IL-6 expression was increased after H. pylori infection, and both IL-6 and IL-11 were strongly up-regulated in gastric cancer tissue." (PMID 26160167, 2015). "We found that, among the analyzed ILs, IL-6, IL-8, and IL-10 levels were significantly different among patients with gastric cancer in comparison to both healthy individuals and patients with other types of gastric malignancies." (PMID 26486258, 2015). "It has been reported that in gastric cancer cells, IL-6 enhanced REG Iα transcription through the STAT3 activation." (PMID 25767811, 2015).
gastric cancer (continued). "The findings suggest that sustained activation of the Jagged-1/Notch signaling in gastric cancer cells elicits an aberrant release of IL-6, leading to the transition of survival signaling, phenotype conversion, and resistance to trastuzumab." (PMID 25669984, 2015). "Since IL-6 reportedly acts as a survival signal as well as a growth signal for gastric cancer cells, Hs738 cells possibly stimulates the growth or survival of gastric cancer cells through IL-6." (PMID 25785838, 2015). "Taken together, our results showed that gastric stromal cells positively regulated the growth of gastric cancer cells through the PGE2-TNFα-IL-6 paracrine pathway, but negatively through secreted GAPDH that bound to E-cadherin." (PMID 25785838, 2015). "In vitro experiments showed that conditioned media of gastric cancer cell lines induced IL-6 secretion by fibroblasts through IL-1 involvement." (PMID 24978438, 2014). "The expression of a subset of these genes—i.e., IL-8, IL-6, and FN-1—along with that of P-p65 was correlated with TP immunoreactivity in gastric cancer tissues." (PMID 25350954, 2014). "In gastric cancer, IL-6 secreted by fibroblasts is considered an important factor involved in the early stage of tumorigenesis." (PMID 24978438, 2014). "This background and the availability of novel IL-6 targeting moAbs prompted us to investigate the possible influence of rs1800795 and rs8192284 on survival of patients with advanced gastric cancer." (PMID 24886605, 2014). "Subjects with gastric cancer, idiopathic thrombocytopenia, or IL-6 > 10 pg/mL were excluded from the study." (PMID 24576354, 2014). "IL-6 was shown to induce cell invasion via activation of c-Src/RhoA/ROCK signalling in a gastric cancer cell line." (PMID 25350954, 2014). "The expression of cell growth-associated IL-6 is higher in the AGS cells than in the MKN45 cells; however, its potential role in gastric cancer cell proliferation has been excluded." (PMID 25398317, 2014). "Comparison of IL-6 expression on human sections, both from healthy donors and diseased patients, and on sections obtained from a mouse model of chemically induced gastric cancer demonstrated higher IL-6 expression by CAFs." (PMID 24978438, 2014). "The localizations of IL-6 and αSMA in many of the same cells were similar to those seen in human gastric cancers, suggesting that stromal fibroblasts expressed IL-6 in the MNU-induced tumorigenesis mouse model." (PMID 23593346, 2013). "We demonstrated that fibroblasts produced IL-6 in response to gastric cancer cells through IL-1 signaling, and that IL-6 promoted tumor growth through STAT3 activation." (PMID 23593346, 2013). "Previous studies of IL-6 in gastric cancer have examined only IL-6 expression in tumor cells or IL-6 levels in the serum of patients with gastric cancer." (PMID 23593346, 2013). "IL-6 plays a key role as a prognostic factor in gastric cancer invasion and lymph and/or hepatic node metastasis, and consistent with our results, in a series of gastric cancer patients, high IL-6 serum levels predict a shorter survival." (PMID 23117246, 2013). "IL-6 plays a positive role as a prognostic factor in lymph node metastasis and advanced gastric cancer." (PMID 23117246, 2013). "Other studies analyzing serum IL-6 levels in patients with gastric cancer revealed that a higher serum IL-6 level was an independent predictor of poor prognosis." (PMID 23593346, 2013). "In patients with gastric cancer, there is an increase in IL-6 and IL-23 compared with the healthy group." (PMID 23554823, 2013). "We showed that stromal fibroblasts were the major source of IL-6, both in human gastric cancers and in chemically induced mouse gastric tumors." (PMID 23593346, 2013). "It seems that the stimulation of production of proinflammatory cytokines such as IL-6 and IL-23 is highest when gastric cancer is still developing." (PMID 23554823, 2013).